IL10 (interleukin 10)
Diseases named in the same sentence as IL10 in open-access papers (continued):
Sharing a sentence is not in itself a finding about the gene and the disease.
glioma (continued). "All three collectively contribute to a pro-tumorigenic glioma TME, despite IL-10 being anti-inflammatory and IL-1β and IL-6 being pro-inflammatory." (PMID 41157253, 2025). "In particular, cytokines such as IL-4, IL-10, and TGF-β secreted by glioma cells, as well as chemokines such as CCL2 and CSF-1, jointly form a complex regulatory network that plays a crucial role in the polarization transition from the M1 type to the M2 type." (PMID 40183013, 2025). "In glioma TME, glioma cells can secrete granulocyte macrophage colony-stimulating factor(GM-CSF), IL-6, IL-10 and other cytokines to stimulate the expansion of MDSC." (PMID 39334448, 2024). "Studies have found that glioma cells express many factors related to the proliferation of MDSCs (IL-6, IL-10, VEGF, PGE-2, GM-CSF, and TGF-β2); however, blocking the chemokine CCL2 signaling pathway in glioma cells effectively reduces the recruitment of MDSCs." (PMID 39206155, 2024). "Glioma cells suppress immune activation by secreting TGF-β and IL-10, while also reducing MHC class II expression on monocytes." (PMID 39452154, 2024). "Results demonstrated that, when cocultured with DHX9‐overexpressed glioma cells, macrophages exhibited decreased expression of M1 markers (IL‐1b, IL‐12b, and TNF‐α) and increased expression of M2 markers (IL‐10, CD163, and ARG1)." (PMID 36377508, 2023). "Overexpression of systemic immunosuppressive soluble factors by glioma cells, such as PTGS2 (rate-limiting step catalyzed by COX-2), TGFB1, IDO1, and IL-10, were also investigated at the transcriptional level." (PMID 37322408, 2023). "We found that TPM4 is related to the molecular targets of glioma, such as CD160, IDO1, IL10, KDR, PVRL2, and TGFB1." (PMID 36639743, 2023). "Glioma cells release a range of chemokines (CSF-1, MCP-1 and others) to recruit and activate TAMs, which then secrete the anti-inflammatory cytokines IL-10 and TGFB1." (PMID 37837549, 2023). "These cells promote tolerance of glioma cells by other effector T cell populations (CD4+ and CD8+) via secretion of transforming growth factor β (TGF-β) and IL-10." (PMID 37046685, 2023). "The proliferative activity of T cells in peripheral blood lymphocytes from glioma patients is reduced when stimulated with T cell mitogens, possibly due to the release of TGF-13 and IL-10." (PMID 37679037, 2023). "Intrinsic tumor resistance, such as the WNT-β-catenin signaling pathway, prevents antitumor immune responses by promoting the release of the immunosuppressive cytokine IL-10 and is a major challenge in ICI therapy for glioma." (PMID 37375698, 2023). "Astrocytes in the glioma microenvironment also secrete cytokines such as TGF-β and IL-10 to inhibit T cell activation." (PMID 37375698, 2023). "Quite the opposite was noted for intermediate monocytes that were characterised by the highest expression of anti-inflammatory IL-10 and TGF-beta with significant up-regulation among glioma patients." (PMID 36768201, 2023). "The glioma microenvironment secretes a variety of immunosuppressive factors, such as TGF-β2, prostaglandin E2 (PGE2), IL-1, IL-10 and fibrinogen-like protein 2 (FGL2)." (PMID 37686020, 2023). "Glioma cells release substances like transforming growth factor-B (TGF-B) and interleukin-10 (IL-10) that hinder the immune response." (PMID 37679037, 2023). "We obtained a positive correlation of FAT1 expression with the expression of IL-10, PD-L1, and PD-L2 genes, the known surrogate markers of MDSCs, in primary and recurrent CGGA glioma cases." (PMID 35720420, 2022). "By producing soluble factors such as IL-10 22, 23, stress inducible protein 1 24, IL1β 25, and CCL8 26, TAMs can activate glioma cell-intrinsic signaling responsible for proliferation, invasion and angiogenesis." (PMID 35673564, 2022). "Gliomas produces cytokines that can recruit MDSCs (i.e. CCL2, CXCL8, SDF-1, CXCL2), as well as cytokines that induce MDSCs expansion (i.e., IL-6, PGE2, IL-10, GM-CSF)." (PMID 36186781, 2022).
glioma (continued). "Immunoregulatory cytokines such as pro-inflammatory factors (IL-1, IL-2, TNF-α, IFN-γ), anti-inflammatory factors (IL-10, TGF-β), and chemokines (CCL-2, CCL-5, CCL-7, CX3CL1) are synthesized and secreted in the microenvironment of glioma." (PMID 34630121, 2021). "TGFB1, VEGFA, ARG1, FGL2 and IL10 are secreted immunosuppressive factors in glioma, while CD95L and CD70 are glioma cell‐surface immunosuppressive factors." (PMID 33611848, 2021). "In glioma patients, TAM BMDM invade the tumor core displaying an anti-inflammatory and pro-angiogenic phenotype, expressing immunosuppressive cytokines (i.e. Il10 and Tgfβ2) and markers of active phagocytosis (CD93)." (PMID 34540682, 2021). "Glioma cells express multiple immune-suppressive cytokines such as transforming growth factor-beta (TGF-β), IL-10, IL-4, IL-6, and IL-13, all of which interfere directly or indirectly with anti-glioma immune response." (PMID 34084145, 2021). "Glioma cells can release multiple immunosuppressive cytokines, such as TGF-β and IL-10, to generate a “cold” tumor microenvironment." (PMID 34646306, 2021). "Tumor recognition and phagocytosis functions of these innate immune cells were declined in glioma milieu, and cytokines such as TGF-β1 and IL-10 they secreted contributed to the formation of immunosuppressive TME." (PMID 34211978, 2021). "Elevated levels of inhibitory cytokines, such as IL-10 and TGF-β, overthrow the balance with proinflammatory molecules contributing to the immunosuppressive microenvironment around glioma." (PMID 34671362, 2021). "Tang el al. observed that, in glioma patients, while only 5.8% of peripheral NKT expressed IL-6 and IL-10, 92.4% of cells in glioma tissues were IL-6+ IL-10+." (PMID 32178454, 2020). "Together with IL6, IL10 and FGF are also known to activate STAT3, which was found to be constitutively activated in glioma." (PMID 33153019, 2020). "In glioma, CSCs can induce M2 macrophages, which secrete many cytokines, including TGF-β1 and IL-10, and facilitate immunosuppression." (PMID 32986017, 2020). "We also found that our model showed a significant increase in cytokines and neurotropic factors, such as IL-10, TGF-β, and G-CSF, which are responsible for tumor progression and glioma genesis compared with the control environment." (PMID 31249133, 2019). "Present in high concentrations within the glioma microenvironment are immunoregulatory cytokines like transforming growth factor-β (TGF-β) and interleukin 10 (IL-10), which support the development of a type-2 polarized environment." (PMID 30386740, 2018). "In our present study, activation of the TLR4 signaling pathway promoted the production of IL-1β, IL-6, IL-10, MCP-1, MIP-1α, and TNF-α in glioma CD133+ CSCs." (PMID 28881826, 2017). "For example, cytokines secreted by M2 macrophages, including IL-10, TGF-β and M-CSF have been shown to promote cell migration and invasion in addition to proliferation in the background of glioma cells." (PMID 27765933, 2016). "Additional pro-proliferation factors such as IL-10, TGF-β and MCP-1, which are also important TAM recruiting factors, were increased in Sr-a1−/− gliomas compared with Sr-a1+/+ gliomas." (PMID 27367025, 2016). "Current data suggest that microglia lose their capacity to express MHC molecules in the context of high-grade gliomas, likely due to the high levels of immunosuppressive cytokines, such as TGF-β, IL-10, and PGE2, within the glioma microenvironment." (PMID 26217588, 2015). "In glioma, however, the antitumour IFN response is impaired by glioma-derivative immunosuppressing factors such as TGF-b, IL-10, prostaglandin E2, and gangliosides." (PMID 25243137, 2014). "Since HCMV secretes a viral homologue of interleukin (IL)–10, which is detected in glioma stem cells, it is possible to adapt a therapeutic method based on targeting HCMV-secreted IL–10 to combat HCMV-related cancers." (PMID 25699089, 2014).
glioma (continued). "Glioma cells express B7-H1, which inhibits T-cell functions via suppression of cytokine production levels (IFN-γ, IL-2, and IL-10) and induction of apoptosis in tumor-specific T-cells." (PMID 24202450, 2013). "Glioma-derived tumor cells are capable of directly secreting immunosuppressive cytokines, including IL6, IL10, and TGF-β, and microglia and astrocytes have also been documented as sources of cytokines." (PMID 22312408, 2012). "Additionally, gliomas secrete immunosuppressive agents, notably TGF-β and IL-10, to create a suppressive TME, thereby dampening the effects of innate immune receptor activation." (PMID 41157253, 2025). "IL10 primarily exerts immunosuppressive effects in the GBM microenvironment by inhibiting effective anti-tumor immune responses and, in some contexts, directly enhancing glioma proliferation via JAK–STAT3 activation." (PMID 41031155, 2025). "Evidence exists that SELP, which is produced by glioma cells, together with its ligand P-Selectin Glycoprotein Ligand-1 (PSGL-1), is able to reduce the phagocytic activity of TAMs and increase the release of the immunosuppressive cytokines TGF-β and IL-10." (PMID 40361384, 2025). "Glioma cells impair the normal functioning of DCs by increasing the secretion of TGF-β and IL-10." (PMID 41268299, 2025). "Notably, there was overexpression of various cytokines, including IL-1β, IL-4, IL-6, IL-8, IL-10, TGF-β and TNF in the patient cohort, which was unsurprising given that these cytokines serve primarily immunosuppressive roles in the glioma microenvironment." (PMID 41034696, 2025). "Additionally, the glioma TME is enriched with immunosuppressive cytokines and growth factors, including transforming growth factor-beta (TGF-β), interleukin-10 (IL-10), and vascular endothelial growth factor (VEGF)." (PMID 41272822, 2025). "For example, Bacteroides fragilis induces the differentiation of Treg cells, thereby promoting the formation of an immunosuppressive microenvironment through the production of immunosuppressive factors such as IL-10 and TGF-β, ultimately contributing to the development of gliomas." (PMID 38737897, 2024). "Production of reactive oxygen species, secretion of nitric oxide, expression of IL-10, TGF-β, and arginase are other possible factors contributing to T cell exhaustion; therefore, immune suppression in glioma microenvironment and poses a challenge for various therapeutic strategies." (PMID 39452154, 2024). "Specifically, we propose that CD180 overexpression in macrophages may affect the secretion of immunomodulatory cytokines (e.g., IL-10, TGF-β) that suppress anti-tumor immunity and promote glioma cell proliferation." (PMID 39707188, 2024). "Additionally, glioma cells and certain immune cells emit a variety of immunosuppressive substances into the TME, including TGF-β and IL-10." (PMID 37744349, 2023). "Important factors expressed by TAMs in gliomas include TNF-ß, high levels of interleukins 6 and 10 (Il-6, Il-10), MMP2 and MMP9, and VEGF and VEGA, which collectively promote glioma proliferation and invasion, angiogenesis and suppression of T effector cell and NK cell activity." (PMID 38275375, 2023). "In addition, gliomas release immunosuppressant cytokines such as TGF-β, IL-10 and cyclooxygenase 2 (COX-2), while simultaneously inhibiting signal transducer and activator of transcription 3 (STAT3), thus enhancing the immunosuppressive microenvironment." (PMID 37686020, 2023). "In addition, MDSCs can promote angiogenesis through the release of VEGF, as well as the release of cytokines such as IL-10, IL-6, and TGF-β under hypoxic conditions, thereby promoting glioma growth and invasion." (PMID 38130720, 2023). "What’s more, by consuming endogenous tryptophan, glioma cells activate AHR and to inhibit T cell function, induce T cell apoptosis, promote CD39 expression, and induce the differentiation of T cells mediated by interleukin 10 (IL-10)." (PMID 36003766, 2022).
glioma (continued). "IL-10 has been shown to enhance the expression of KPNA2, which affects cell growth and expression in cancer cells, including the human brain tumor, suggesting that IL-10 promotes glioma cell growth and invasion by regulating KPNA2." (PMID 36009467, 2022). "Recently, we have reported that in the glioma microenvironment, levels of IL4, IL13, IL10, and TGFβ are increased by the IFNG response, which constitute a regulatory network of inflammatory responses and ultimately drives macrophages toward M2-type polarization." (PMID 35492352, 2022). "This may be due, in part, to increase expression of immunosuppressive factors, like programmed cell death 1 ligand (PD-L1), interleukin 10 (IL-10), indolamine 2,3-dioxygenase (IDO), and transforming-growth factor β (TGF-β), in the glioma microenvironment." (PMID 35592529, 2022). "CMV IL-10 can bind to the human IL-10 receptor and activate the STAT3 transcription factor, which plays a key role in immune suppression and tumorigenesis, especially in gliomas." (PMID 33668202, 2021). "In response to these signals, GAMs release multiple cytokines such as transforming growth factor ß (TGF-β), stress-inducible protein 1 (STI-1), prostaglandin E2 (PGE2), IL-6, IL-1β, IL-10, and epidermal growth factor (EGF), which promote glioma cell proliferation and inhibit T cells function." (PMID 34084145, 2021). "EV-miR-1246 from hypoxic glioma cells reprograms macrophages into M2 phenotype by targeting TERF2IP, which further enhances the proliferation, migration and invasion of glioma cells in vitro and in vivo probably by secreting IL10, TGF-β." (PMID 32503543, 2020). "In 63 adult patients with gliomas and 31 healthy controls, the expressions of TREM-1 and TREM-2 on CD14+ blood cells (method: flow cytometry) and the levels of soluble sTREM-1, HMGB1, IL-6, and IL-10 (Elisa tests) were analyzed." (PMID 32684831, 2020). "Thus, we analyzed the expression of a panel of common M1 (IL-1b, IL-12, iNOS, TNFα) and M2 (TGFβ, IL-10, ARG1) phenotype markers and the immune suppressive PD-L1 (CD274) in control and Pdpn-deleted BMDM co-cultivated with four different glioma cell lines." (PMID 30972297, 2019). "Furthermore, we observed that systemic levels of IL-8 and IL-10 differed according to the tumor grade, with higher levels in patients with glioblastoma (WHO grade IV) compared to lower grade glioma (WHO grade II–III)." (PMID 31847343, 2019). "Early studies demonstrated that PD-L1 expressed by glioma cells inhibits T-lymphocyte functions and induces apoptosis of tumor-specific T-lymphocytes mainly via decreasing cytokines production (e.g., IFN-γ, IL-2 and IL-10)." (PMID 30687086, 2018). "In our work we provide evidence that GSC-derived exosomes are involved in the conversion of monocytes to arginase-1- and IL-10-producing Mo-MDSC cells that contribute to T cells immunosuppression without the necessity of direct contact between monocytes and glioma cells." (PMID 28107450, 2017). "Having found that IL-10 secreted from M2 macrophages was dependent on the JAK2/STAT3 signaling pathway and that co-culture with glioma cells was able to activate the JAK2/STAT3 signaling pathway in M2 macrophages, we've next tried to understand how IL-10 was dependent on JAK2/STAT3 pathway." (PMID 27765933, 2016). "The exact function of IL-10 in glioma is not clear; further studies are required to elucidate the mechanisms underlying the association between IL-10 polymorphisms and glioma patient prognosis." (PMID 27811370, 2016). "IL-10 inhibits human T cell proliferation by downregulation of MHC class II expression, inhibiting the antigen-presenting capacity of monocytes and subsequently promotes glioma tumor growth." (PMID 25793261, 2015). "Various factors produced by glioma cells might contribute to these defects such as TGFβ, PGE2, and IL10." (PMID 20953324, 2010).
glioma (continued). "In addition to these, MAPKAPK2 is positively correlated with IL6, IL6R, IL10, IL10RB, TGFβ1, etc., in the present study, which may facilitate the glioma progression." (PMID 38322416, 2024). "Furthermore, exogenous consumption of tryptophan resulted in glioma cells activating AHR which inhibited T cell function, induced T cell apoptosis, promoted CD39 expression, and induced differentiation of T cells mediated by interleukin 10 (IL-10)." (PMID 39594997, 2024). "However, the immunosuppressive environment of high-grade gliomas, including vascular endothelial growth factor (VEGF), prostaglandin E2 (PGE2), and IL-10 expression, may induce a regulatory or tolerant dendritic cell phenotype." (PMID 36768342, 2023). "Our initial finding was that hypoxic glioma‐derived EVs could promote macrophages M2 polarization, as evidence by decreased expression of iNOS and TNF‐α as well as elevated expression of Arg‐1 and IL‐10." (PMID 36052751, 2022). "PD-L1 expressed by glioma, in addition to increasing the number of T-reg cells, inhibits the functions of T lymphocytes and induces apoptosis of tumor-specific CD4+ and CD8+ T lymphocytes by decreasing the production of cytokines such as Inter-leukin-2 (IL-2) and interleukin-10 (IL-10)." (PMID 36555334, 2022). "Furthermore, glioma-related B7-homologue 1 (B7-H1) was identified as a strong inhibitor for activating CD4+ and CD8+ T-cell, evaluated by the increase of cytokine production, such as IFN-γ, IL-2, IL-10, and the expression of CD69, the T-cell activation marker." (PMID 35269652, 2022). "The inactivation of T cells may also come from IL-10 and TGF-β released by glioma cells." (PMID 34671362, 2021). "Glioma highly inhibits tumor immunity, and glioma cells produce immunosuppressive factors such as TGF-β, IL-10 and indoleamine–pyrrole 2, 3-dioxygenase (IDO) Glioma also expresses immune checkpoint ligand to inhibit immune response, so it is difficult to use immunotherapy to treat glioma." (PMID 34630121, 2021). "After migrating into the glioma environment, TAMs tend to possess the M2 phenotype, and their differentiation is driven by the secretion of immunosuppressive factors, including CSF-1, CCL2, IL-4, IL-6, IL-10, and transforming growth factor (TGF- β), from tumor cells." (PMID 30619286, 2018). "Furthermore, it has been demonstrated that glioma cell-derived conditioned medium is able to increase STAT3 activity in microglia cells, leading to increased secretion of the anti-inflammatory M2-like cytokines IL-6 and IL-10." (PMID 29389898, 2018). "Taking together, we for the first time found that IL-10 from M2 macrophage promoted proliferation of glioma through interaction with JAK2; thereby activating the JAK2/STAT3 pathway, indicative of IL-10 could be used as a therapeutic target in the curing of glioma." (PMID 27765933, 2016). "Secondly, Whether or not blocking of IL-10 could inhibit other signaling pathway mainly involved in the carcinogenesis of glioma remains to be studied." (PMID 27765933, 2016). "Whether or not similar soluble factors are utilized by gliomas and systemic tumors to induce TAMs to produce IL-10 is still unknown, but such knowledge would be therapeutically relevant for targeting IL-10 in these tumors." (PMID 26217588, 2015). "Furthermore, in a recent series of similar experiments, monocytes isolated from healthy subject dramatically increased expression of both IL-10 and TGF-β following co-culture with glioma cell lines, as compared to isolated culture as well as co-culture with NHA." (PMID 23737783, 2013). "However, the distinctively immune-privileged microenvironment that is formed due to the intrinsic expression of immunosuppressive cytokines, such as PD-1, PD-L1, TGF-β and IL10, and the lack of antigen-presenting cells (APCs) in the CNS result in challenges for glioma patient prognosis." (PMID 37779195, 2023).